INS (insulin)
Diseases named in the same sentence as INS in open-access papers (continued):
Sharing a sentence is not in itself a finding about the gene and the disease.
diabetes (continued). "Accordingly, cardiac insulin resistance also attenuates the direct inhibitory effects of insulin on fatty acid β-oxidation, which further increases fatty acid β-oxidation rates Cardiac insulin resistance decreases insulin-stimulated glucose uptake in diabetes." (PMID 34831481, 2021). "Four genes including GAB2, LMNB2, XAB2 and RBM39 are involved in the regulation of diabetes, fat and insulin signaling, according to text mining." (PMID 34084770, 2021). "Diabetes mellitus (DM) is a heterogeneous group of physiological dysfunctions characterized by hyperglycemia, insulin resistance, insufficient insulin secretion, or glucagon hypersecretion." (PMID 33676437, 2021). "Curcumin has a strong synergistic effect that enhanced the stability of insulin glycemic control and anti-apoptotic ability as well as maintain the homeostasis of Nrf2 endogenous antioxidant pathway in the early stages of diabetes." (PMID 34955862, 2021). "Diabetes mellitus (DM) is a frequently encountered chronic metabolic disease which is characterized by elevated plasma glucose level resulting from inadequate insulin secretion and/or increased insulin resistance." (PMID 33520315, 2021). "Only 14% of the population had T2DM, and diabetes remission was not reported, although the greatest and most sustained reduction in fasting glucose and insulin amongst people with diabetes occurred with the Mediterranean diet." (PMID 33369151, 2021). "Diabetes mellitus can be divided into two major types: Type 1 diabetes mellitus, characterized by the destruction of pancreatic β-cells, and type 2 diabetes mellitus, characterized by impaired insulin secretion and insulin resistance." (PMID 34681566, 2021). "The average score of the Diabetes Treatment Satisfaction Questionnaire22 was 26.4 (5.6) at baseline, 26.9 (5.7) after sensor-augmented pump therapy, and 28.2 (5.5) after automated insulin delivery." (PMID 33050728, 2021). "In the near future, patient access to advanced technology, like automated insulin delivery (close loop) systems, is anticipated to improve, and thus, the importance of diabetes technology education will increase." (PMID 33258970, 2021). "In contrast to CK2, which is upregulated in skeletal muscle of patients with diabetes mellitus type 2, PERM1 is decreased, further supporting a close association with insulin-dependent metabolism and mitochondrial activity." (PMID 34385433, 2021). "Diabetes, as we know, is a chronic disease with multiple etiologies characterized by abnormal glucose tolerance and carbohydrate metabolism due to defective insulin secretion, insulin resistance, or both." (PMID 34778463, 2021). "Previous quantitative research suggested that insulin-treated T2DM patients have experienced significantly higher diabetes distress, particularly regimen-related distress." (PMID 35002853, 2021). "The sample is representative of the diabetes population at risk of DR because about 75% had lived more than 4 years with known diabetes, 60% had uncontrolled diabetes and about a third had systolic BP ≥ 140 mmHg and were already on insulin treatment." (PMID 34945199, 2021). "In type 2 diabetes (T2D), which accounts for 90-95% of all diabetes, a combined resistance to insulin both in skeletal muscle and the liver, in addition to defective insulin production by pancreatic β cells is present." (PMID 34149714, 2021). "Although there are numerous hypoglycemic drugs known, such as insulin analogs, metformin, sulfonylureas, thiazolidinediones, sodium-glucose co-transporter-2 inhibitors, or acarbose, the diabetic disease progresses over time." (PMID 34067862, 2021). "Immunoreactivity in the Diabetes group had dramatically reduced according to the control group and only a few β-cells displayed minimal insulin immunoreaction." (PMID 33520200, 2021). "One area of diabetes research focuses on finding new approaches to regenerate sufficient endogenous insulin-secreting β-cells for optimal blood glucose regulation." (PMID 33239359, 2021).
diabetes (continued). "Clearly, the weight gain associated with the use of thiazolidinediones (pioglitazone and rosiglitazone), sulphonylureas (glibenclamide), and insulin is also the major drawback for treating diabetes." (PMID 34527069, 2021). "Epidemiological studies have indicated that the increased intake of dietary soy isoflavones positively correlates with a lower incidence of diabetes and increased tissue sensitivity to insulin." (PMID 34769332, 2021). "As continuous subcutaneous insulin infusion (CSII) usage to aid diabetes management becomes more widespread, there is still uncertainty regarding its effectiveness and safety." (PMID 33686483, 2021). "Magnesium deficiency is usually associated with T2DM, increased insulin resistance and reduced insulin secretion, thus contributing to uncontrolled diabetes." (PMID 34842632, 2021). "In contrast to the substantial body of work focused on insulin secretion, relatively fewer studies have examined the role of insulin clearance in the development of diabetes." (PMID 34206745, 2021). "Other animal experiments have further confirmed that under high-fat conditions, S1P can mobilize a large amount of insulin secretion and delay the occurrence of diabetes." (PMID 34751249, 2021). "This suggests almost all people with insulin-treated diabetes and one or two DR15-DQ6 haplotypes have type 2 diabetes." (PMID 34272580, 2021). "Results were adjusted for age, pre-existing diabetes mellitus, severity of illness, and total insulin and glucocorticoid dose." (PMID 33755703, 2021). "I have to take diabetes medicine and have insulin injection 20-0-16, and I have difficulty seeing due to my eye problems." (PMID 34415236, 2021). "IR content reduction has long been suspected to contribute to the defective insulin signaling and diabetes progression." (PMID 34029592, 2021). "The EDBS has six subscales which include worry about diabetes, symptom burden, treatment dissatisfaction, burden by tablets or insulin, dietary restrictions and social burden." (PMID 34501838, 2021). "According to the World Health Organization, diabetes is defined as a chronic metabolic disease characterized by an incorrect glucose metabolism resulting from defects in insulin secretion or insulin action." (PMID 34073550, 2021). "It is challenging to achieve stable basal concentrations and those with insulin-treated diabetes are subject to both hyper- and hypoglycaemia." (PMID 34814734, 2021). "Insulin signal plays a critical role in the metabolic process and insulin resistance usually accompanies obesity, diabetes, and several other metabolic diseases." (PMID 33637697, 2021). "Though often referred to as a single condition, diabetes is likely many overlapping diseases, with most stemming from pancreatic β-cell dysfunction and the disruption of glucose homeostasis due to abnormal insulin secretion and/or responsiveness." (PMID 34149620, 2021). "Patients with established CVD were older and had significantly higher rates of insulin treated diabetes, chronic obstructive pulmonary disease, renal impairment, congestive heart failure, and unstable angina." (PMID 34432113, 2021). "There are several components of diabetes management including nutrition therapy, insulin therapy, and other glucose-lowering medications." (PMID 33918343, 2021). "She had two cousins with diabetes on insulin treatment at 18 and 24 years of age who were also diagnosed during infancy (patients number 6.7 and 6.8)." (PMID 32820876, 2021). "The two most distinguished types of diabetes are type 1 and type 2 diabetes, resulting from the autoimmune impairment of insulin-generating pancreatic β cells and insulin insensitivity, respectively." (PMID 34603195, 2021). "Many patients with type 2 diabetes mellitus have an increase in treatment escalation in order to achieve glycaemic targets over time, ultimately with a high proportion progressing to insulin-based therapy." (PMID 34448033, 2021).
diabetes (continued). "As a result, enhance the possibility that all patients with diabetes worldwide that need insulin to control their diabetes have access to the same range of insulin preparations to improve the management of their condition." (PMID 34249838, 2021). "Contrary to this, HIF1 is stabilized by both insulin and IL-1, which are overexpressed in diabetes under normoxic condition." (PMID 34225729, 2021). "For insulin diabetes medicines there was a 2.3% growth of prescriptions from January to November 2020, compared to the same months in 2019, in the range of previous years’ growth (1.8% in 2017, 2.5% in 2018, −0.1% in 2019)." (PMID 34209616, 2021). "In order for the pancreas to compensate for this condition, there must be an increase in insulin synthesis, so that disorders at the level of pancreatic cells will secrete less insulin and the result will be the development of diabetes and hyperglycemia." (PMID 33401397, 2021). "This is a limitation of the present study since insulin production and insulin sensitivity are indeed important mechanisms in the complex pathogenesis of diabetes." (PMID 34059937, 2021). "Specifically, the results demonstrated that AME improved insulin metabolism, lipid metabolism, and autophagy pathway which are related with non-alcoholic fatty liver disease (NAFLD) risk in type 2 diabetes mellitus (T2DM)." (PMID 34679681, 2021). "METTL3 significantly modulated HFD-induced metabolic disorders, insulin sensitivity, and hepatogenic diabetes." (PMID 34084770, 2021). "In the setting of diabetes, defects in δ-cell function lead to suboptimal insulin and glucagon outputs and lift the glycemic set-point." (PMID 33494193, 2021). "The idealized solution to the diabetes mellitus pandemic would be islet and pancreatic transplantation for endogenous insulin release." (PMID 34959394, 2021). "In conclusion, the manifestation of TIND induced by insulin treatment in BB/OKL rats has been linked to the magnitude and timing of a marked reduction in HbA1c, as was suggested in patients with type 1 diabetes mellitus." (PMID 33557206, 2021). "Its mechanisms for the induction of diabetes are inhibition of insulin secretion and the death of the beta-cells." (PMID 33995939, 2021). "Diabetes is a metabolic disease that involves the death or dysfunction of the insulin-secreting β cells in the pancreas." (PMID 34201511, 2021). "Type 2 diabetes mellitus (T2DM) is a subtype of diabetes mellitus (DM) characterized by progressive dysfunction of β-cell insulin secretion and insulin resistance (2." (PMID 34552482, 2021). "Diabetes is characterized by chronic hyperglycemia resulting from the body’s inability to meet its insulin requirements." (PMID 34040585, 2021). "Regenerative therapeutic approaches involving the transplantation of stem cells differentiated into insulin‐producing cells are being studied in patients with rapidly progressing severe diabetes." (PMID 33759360, 2021). "It was confirmed that serum calcium levels were directly correlated to glucose intolerance, insulin resistance, impaired glucose metabolism, early-phase insulin secretion, and diabetes." (PMID 34434908, 2021). "Diabetes mellitus (DM) is a common metabolic disorder characterized by chronic hyperglycemia due to the effects of insulin secretion or insulin action." (PMID 33747864, 2021). "The third woman with type 1 diabetes mellitus intentionally missed her insulin doses to induce diabetic ketoacidosis and gain familial empathy through recurrent hospital admission, with underlying suicidal ideation." (PMID 34040920, 2021). "Studies in humans and mice have postulated that over-replacement of insulin in patients with diabetes produces a general anabolic effect that leads to increased fat accumulation and weight gain." (PMID 34579668, 2021). "Most oral diabetes medications are contraindicated in people with ESRD, so insulin is the most commonly used diabetes therapy." (PMID 34349267, 2021).
diabetes (continued). "Other therapies, such as β-cells regeneration and gene therapy, in addition to insulin and oral hypoglycemic drugs, are currently used to control diabetes." (PMID 34683861, 2021). "There were notable differences with respect to age, race/ethnicity, weight, body mass index, length of stay, diabetes type, use of home insulin, and use of insulin secretagogues by hospital." (PMID 33416883, 2021). "Many GPs had found that patients refused to take insulin due to a fear of needles and a feeling that using insulin means they had “failed” at managing their diabetes." (PMID 34275440, 2021). "Defects in the insulin/insulin-like growth factor signaling pathway (insulin/IGF signaling or IIS) manifest as a metabolic syndrome, a precursor to the onset of type 2 diabetes mellitus (T2DM) associated with an increased risk of some cancers." (PMID 33672471, 2021). "Even for those with type 2 diabetes where insulin sensitivity in the cells is decreased, diabetic ketoacidosis is rare since these catabolic processes are very sensitive to insulin." (PMID 34063366, 2021). "Third, diabetes is a systemic disease characterized by decreased insulin sensitivity in metabolic tissues and organs, which can damage the structure and function of various tissues and organs in the body." (PMID 33588950, 2021). "Diabetes mellitus (DM) results from the inability of the pancreas to produce sufficient insulin or weakened cellular response to the insulin produced, which leads to hyperglycemia." (PMID 34885816, 2021). "The buccal administration of insulin for the management of diabetes has received substantial attention worldwide." (PMID 33923670, 2021). "A recent study that jointly modeled the three aspects of insulin homeostasis also found that insulin resistance had a greater magnitude of effect on incident diabetes than decreased insulin secretion and decreased insulin clearance." (PMID 34206745, 2021). "We discuss the potential of both stem cell‐derived pancreatic progenitors and more matured insulin‐producing cells to treat diabetes." (PMID 34387389, 2021). "Since patient 1 suffered from severe diabetes, insulin therapy was started since the age of 12 years." (PMID 34342583, 2021). "Diabetes mellitus is one of the most common metabolic disorders, characterized by insulin malfunction and hyperglycemia due to inadequate insulin secretion, or both of them." (PMID 33430013, 2021). "APPL2 expression has been related to adiponectin and thus to obesity, insulin metabolism, and diabetes." (PMID 34930449, 2021). "The advent of insulin replacement therapy in the early 1900s and the increased efforts toward metabolic control of diabetes mellitus (DM) through oral hypoglycemic agents have certainly improved the life quality and expectancy of subjects with diabetes." (PMID 34901269, 2021). "These hospitalizations were systematically selected by the Agency for Healthcare Resources and Quality (AHRQ) and we included all type 1 diabetes mellitus patients over the age of 18 who were on insulin, either pump or injections, in our study." (PMID 33668749, 2021). "Whenever the pancreatic capacity to sustain insulin hypersecretion is overridden, circulating glucose levels increase and pre-diabetes or overt T2D occurs." (PMID 34071774, 2021). "Diabetes, as a growing public health problem, is characterized by impairment of systemic insulin secretion, reduction of insulin action, and resulting in hyperglycemia." (PMID 33995939, 2021). "Alterations in insulin signaling and production, as observed in insulin resistance, significantly impair glucose homeostasis in several pathological conditions, such as diabetes, hypertension, and heart failure." (PMID 33467677, 2021). "Three main categories of diabetes exist: T1DM is triggered by an autoimmune reaction where the immune system of the body destroys the insulin-producing β-cells of the pancreas." (PMID 34683861, 2021).
diabetes (continued). "The current study was conducted to assess the association of IR with AD at KAMC-J and to study the relationship of AD with diabetes treated with insulin." (PMID 34956794, 2021). "Other research has demonstrated that this natural sweetener increases insulin sensitivity, reduces gluconeogenesis, and prevents oxidative DNA damage related to type 2 diabetes mellitus." (PMID 34578870, 2021). "Rosiglitazone (ROSI) is another high-affinity PPAR-γ agonist, a second-generation TZD, originally developed as an insulin sensitizer for the treatment of diabetes." (PMID 34631571, 2021). "It is believed that the onset of double diabetes begins with inadequate levels of circulating insulin, which results in an increase in muscle lipid flux that the mitochondria are unable to metabolize." (PMID 34229671, 2021). "β-cells of the pancreatic islets secrete insulin and play a major role in glycemic control and the development of diabetes." (PMID 34174896, 2021). "Approximately 32.4% had diabetes (24.6% insulin-dependent and 7.5% non–insulin-dependent), 68.3% used marijuana, and 26.6% were on chronic opioids." (PMID 34060494, 2021). "Insulin therapy is one of the most common methods to control blood glucose in patients with Type 2 diabetes mellitus (T2DM)." (PMID 33598483, 2021). "T2DM accounts for about 90% of all diabetes cases, resulting from insulin resistance combined with impaired insulin secretion." (PMID 34447287, 2021). "Diabetes is characterized by impaired carbohydrate, protein, and fat metabolism that results from poor insulin secretion, insulin resistance, or both." (PMID 34222073, 2021). "Before the invention of the first manufactured insulin in 1978, dealing with diabetes took a significant toll on patient's lives." (PMID 34540446, 2021). "Individuals with the cardiac risk factors obesity, arterial hypertension, dyslipidemia, or diabetes should also perform resistance training ≥3 times per week to improve hemoglycemic control and insulin sensitivity." (PMID 33567725, 2021). "We included four RCTs with 534 participants (349 in the insulin degludec group and 185 in the insulin glargine group) with type 2 diabetes mellitus (T2DM)." (PMID 34345540, 2021). "In these reports, it has remained unclear which diabetes-related factor, such as hyperglycemia, the reduction of insulin level, or antidiabetic agents, affects these expression changes." (PMID 34493754, 2021). "Regenerative therapy using insulin-producing cells derived from stem cells has been studied as a radical treatment approach for type 1 diabetes mellitus." (PMID 34681566, 2021). "GLP-1 receptor agonists and GLP-1 enhancers have been clinically employed to treat diabetes owing to their glucose-dependent insulin-releasing activity." (PMID 34205659, 2021). "Unstable metabolic control and high risk of hypoglycemia due to GV is frequently observed in patients with diabetes on intensive insulin therapy." (PMID 34876671, 2021). "Both PD and diabetes manifest clinical features when the action of a chemical messenger (dopamine in PD and insulin in diabetes) is reduced." (PMID 34208795, 2021). "One hundred years ago, insulin was purified and administered to people with diabetes to lower blood glucose, suppress ketogenesis and save lives." (PMID 34841432, 2021). "Diabetes mellitus (DM) is a metabolic disorder characterized by high blood glucose levels that occurs either due to insufficient insulin production or mounting resistance to its action." (PMID 34970629, 2021). "Generations of insulin-producing cells and pancreatic progenitors from stem cells are potential therapeutic methods for treating diabetes and diabetes-related diseases." (PMID 34977045, 2021). "The chronic nature of diabetes means that patients require long-term insulin treatment, and this can place heavy financial burden on the healthcare systems and individuals." (PMID 34336550, 2021).